ACKR3 (atypical chemokine receptor 3)
Diseases named in the same sentence as ACKR3 in open-access papers (continued):
Sharing a sentence is not in itself a finding about the gene and the disease.
pulmonary fibrosis (10 papers, 2020 to 2024). Chronic progressive interstitial lung disorder characterized by the replacement of the lung tissue by connective tissue, leading to progressive dyspnea, respiratory failure, or right heart failure. "In preclinical models of liver and lung fibrosis, ACKR3 was previously shown to be upregulated after acute injury in liver sinusoidal and pulmonary capillary endothelial cells, respectively." (PMID 35562519, 2022). "Incidentally, ACKR3/CXCR7 expression is also reduced in patients with interstitial pulmonary fibrosis." (PMID 35053329, 2022). "Whereas twice daily in vivo administration of the ACKR3 agonist lacked inhibitory effect on bleomycin-induced lung fibrosis, it had a modest, but significant anti-fibrotic effect in the carbon tetrachloride (CCl4)-induced liver fibrosis model." (PMID 35562519, 2022). "In conclusion, whereas the TC14012 ACKR3 agonist successfully attenuated fibrosis in liver and lungs, the ACKR3 agonist compound 18a was not effective in reducing lung fibrosis, but modestly attenuated fibrosis in the liver." (PMID 35562519, 2022). "Some recent reports have shown that ACKR3 is highly expressed in lung tissue and that the ACKR3 agonist TC14012 can decrease collagen I deposition and can protect the alveolar epithelial structure and function in a mouse model of bleomycin-induced lung fibrosis." (PMID 34098338, 2021).
Stroke (10 papers, 2013 to 2023). Sudden impairment of blood flow to a part of the brain due to occlusion or rupture of an artery to the brain. "In human, expression levels of both CXCL12 and ACKR3, but not that of CXCR4, are increased in the peri-infarction area of ischemic cerebral cortex, suggesting that CXCL12 modulates the repair of the brain after a stroke through ACKR3 activation." (PMID 35846294, 2022).
bladder cancer (9 papers, 2013 to 2024). "Among atypical receptors, CXCR7 (ACKR3) has been reported to induce EMT and sustain tumor development in bladder cancer." (PMID 32784743, 2020).
Obesity (9 papers, 2018 to 2025). Accumulation of substantial excess body fat. "Atypical chemokine receptor 3 (ACKR3) expression was shown to increase in AT during obesity, and its ubiquitous elimination caused hyperlipidemia in mice." (PMID 33917642, 2021). "Additionally, ACKR3 was shown to be upregulated in AT during obesity in Western diet (WD)-fed mice, suggesting that adipocyte ACKR3 may be involved in the pathology of obesity." (PMID 33917642, 2021). "Among them, the upregulated gene BCL2A1 is common in CVD, HTN, obesity, and aging; RNF144B and PTGIS are common in HCL, obesity, aging, and CVD; G0S2, CXCL1, ACKR3, and PTPRD are found in HTN, aging, and CVD; TGFB2, CA12, and MSR1 are familiar in obesity, aging, and CVD." (PMID 36035865, 2022).
renal carcinoma (9 papers, 2012 to 2026). A carcinoma arising from the epithelium of the renal parenchyma or the renal pelvis. "ACKR3 is overexpressed in many human cancers, including renal carcinoma, and is correlated with poor prognosis, tumor progression, and metastasis." (PMID 38067341, 2023). "ACKR3 is also expressed by aggressive prostate carcinoma cells and in renal carcinoma patients with decreased survival and poor prognosis." (PMID 30894861, 2019).
leukemia (8 papers, 2014 to 2025). A malignant (clonal) hematologic disorder, involving hematopoietic stem cells and characterized by the presence of primitive or atypical myeloid or lymphoid cells in the bone marrow and the blood. "The CXCL12/CXCR4/ACKR3 axis plays a pivotal role in regulating the migration, dissemination, and homing of leukemia cells." (PMID 38920657, 2024). "Reviews have highlighted that the CXCL12/CXCR4/ACKR3 axis can activate the STAT3 pathway, leading to leukemia development." (PMID 38920657, 2024).
multiple sclerosis (8 papers, 2020 to 2025). A progressive autoimmune disorder affecting the central nervous system resulting in demyelination. "Imbalances in the CXCL12/CXCR4/ACKR3 axis are associated with diseases, including cancer, multiple sclerosis, and RA." (PMID 34489952, 2021).
diabetes (7 papers, 2021 to 2025). "Previously, a PPAR-γ stimulating drug used in type 2 diabetes mellitus treatment (pioglitazone) was shown to inhibit ACKR3 expression in differentiated macrophages which resulted in suppressed chemotaxis." (PMID 33917642, 2021).
esophageal cancer (7 papers, 2013 to 2025). A primary or metastatic malignant neoplasm involving the esophagus. "In vivo tumor transplantation experiments have also revealed that the upregulation of ACKR3 enhances the expression of Ki67 in tumor tissues, thereby promoting the growth and metastasis of esophageal cancer." (PMID 38920657, 2024). "Moreover, it was found that MIF bind to ACKR3 (atypical chemokine receptor 3) and increases esophageal cancer migration and invasion." (PMID 41159021, 2025). "In esophageal cancer, in vitro experiments have demonstrated that the CXCL12/ACKR3 axis activates the STAT3 pathway." (PMID 38920657, 2024).
heart failure (7 papers, 2021 to 2024). Inability of the heart to pump blood at an adequate rate to meet tissue metabolic requirements. "Expression of ACKR3 is significantly increased in the infarct border zone of mouse heart and in heart failure patients." (PMID 35846294, 2022). "ACKR3 expression is increased in cardiomyocytes of patients with heart failure." (PMID 35846294, 2022). "However, the initial active player M_SH, co-expressing Ackr3, Cd34, Cd248, and Pi16, was reported as cardiac mesenchymal-like stem cells with multilineage differentiation and self-renewal capacities, and promoted heart failure." (PMID 37147443, 2023).
diffuse large B-cell lymphoma (6 papers, 2017 to 2022). "Here, we propose a model of how ACKR3 controls the migration of the diffused large B-cell lymphoma VAL cells in vitro and in vivo in response to CXCL12." (PMID 36713377, 2022). "ACKR3 is upregulated in ALL, as well as AML, and is necessary for colonization of the draining lymph node in diffuse large B cell lymphoma." (PMID 32817744, 2020). "In mucosa-associated lymphoid tissue (MALT) neoplasms upregulation of ACKR3 and concomitant downregulation of CXCR4 could play a role in the transformation to diffuse large B-cell lymphoma (DLBCL)." (PMID 29156704, 2017).
ischemia (6 papers, 2020 to 2025). A hypoperfusion of the BLOOD through an organ or tissue caused by a PATHOLOGIC CONSTRICTION or obstruction of its BLOOD VESSELS, or an absence of BLOOD CIRCULATION. "Activation of the CXCL12/CXCR4/ACKR3 axis is known to aid myocardial repair through ischemia-triggered hypoxia-inducible factor-1α (HIF-1α)." (PMID 38994928, 2024). "HIF-1α is a crucial transcription factor in the cardiovascular system, as it regulates gene expression of the CXCL12/CXCR4/ACKR3 axis during ischemia." (PMID 38994928, 2024). "In addition, animals carrying this platelet specific Ackr3 knockout showed increased damage and inflammation of the myocardium and brain after ischemia/reperfusion." (PMID 39373210, 2025). "Interestingly, conditional specific deletion of Ackr3 in cardiomyocytes (αMHC-Cre+/− CXCR7flox/flox model) in mice leads to excessive left ventricular dilatation and major systolic dysfunction after MI demonstrating that cardiomyocyte ACKR3 protects the heart after ischemia." (PMID 35846294, 2022). "Thus, it is tempting to hypothesize that both platelet (early phase of I/R) and endothelial (chronic occlusion and myocardial remodeling) ACKR3 play a critical role in the pathophysiology of myocardial repair following ischemia." (PMID 35383158, 2022).
liver fibrosis (6 papers, 2015 to 2024). "In this study, we further embarked upon this protective role of ACKR3 activity by evaluating an ACKR3-specific small molecule agonist (compound 18a) in preclinical mouse models of lung and liver fibrosis." (PMID 35562519, 2022). "This may explain the rather modest effect on liver fibrosis of the selective ACKR3 agonist we tested here, compared to TC14012 with its combined (opposite) activity on both receptors." (PMID 35562519, 2022). "Interestingly, expression of ACKR3 was mostly upregulated in the latter cluster in livers with cirrhosis, an advanced stage of liver fibrosis." (PMID 35562519, 2022). "It remains to be determined whether ACKR3 agonism in the liver, like in the heart, has a pro-angiogenic effect and whether this has a beneficial or rather detrimental effect on liver fibrosis." (PMID 35562519, 2022). "Furthermore, the fact that the ACKR3 agonist compound 18a increased the bioavailability of CXCL12 (which can act as an agonist on the CXCR4 receptor) may even have counterbalanced the beneficial effect on liver fibrosis." (PMID 35562519, 2022). "This suggests that the impact of ACKR3 agonism is rather important in the early stages, while CXCR4 antagonism becomes more important in the chronic phase of liver fibrosis." (PMID 35562519, 2022). "The selective profile of this small molecule (i.e., being a potent ACKR3-agonist without CXCR4 antagonism) allowed us to evaluate the role of pure ACKR3-agonism, thus ruling out the potential additional effect of CXCR4 antagonism, in mouse models of lung and liver fibrosis." (PMID 35562519, 2022). "Therefore, applying compound 18a in the in vivo lung and liver fibrosis models allowed us to evaluate the anti-fibrotic effect of pure ACKR3 agonism in the absence of CXCR4 antagonism, which has never been addressed before." (PMID 35562519, 2022).
acute coronary syndrome (5 papers, 2015 to 2023). Signs and symptoms related to acute ischemia of the myocardium secondary to coronary artery disease. "Expression of ACKR3 in platelets is increased post-MI in mice and patients with acute coronary syndrome and is associated with improved cardiac function and prognosis." (PMID 35846294, 2022). "ACKR3 is also constitutively expressed in human and murine platelets ant its expression is upregulated in patients with acute coronary syndrome." (PMID 35846294, 2022).
Cerebral ischemia (5 papers, 2013 to 2023). Restriction of arterial blood supply to the brain associated with insufficient oxygenation to support the metabolic requirements of the tissue. "Recently, neutralization of ACKR3 with a specific blocking antibody following cerebral ischemia resulted in significantly enhanced neurogenesis in the hippocampal associated to cognitive functional recovery." (PMID 35846294, 2022).
Insulin resistance (5 papers, 2021 to 2025). Increased resistance towards insulin, that is, diminished effectiveness of insulin in reducing blood glucose levels. "Insulin resistance-related pathways were also observed when analyzing miRNA targets following ACKR3 stimulation." (PMID 40667070, 2025).
peritonitis (5 papers, 2019 to 2024). Inflammation of the peritoneum (tissue that lines the abdominal wall and covers most of the organs in the abdomen). "Infiltrating monocytes in a mouse peritonitis model as well as lesional macrophages in aortic atheroma of mice showed increased ACKR3 expression, pointing toward an inflammatory role of ACKR3." (PMID 31191301, 2019).
rhabdomyosarcoma (5 papers, 2010 to 2022). A rare aggressive malignant mesenchymal neoplasm arising from skeletal muscle. "In a study investigating the CXCL12/CXCR4/ACKR3 axis in rhabdomyosarcomas, ACKR3 promoter activity was shown to depend on an NF-κB binding site." (PMID 35674847, 2022).
cardiac hypertrophy (4 papers, 2021 to 2022). "Overexpressing of Adm in mice caused cardiac hypertrophy during embryogenesis similar to that observed in Ackr3-/- animals." (PMID 35846294, 2022). "However, pharmacological targeting of ACKR3/CXCR7 by administration of CXCR7-agonist TC14012 retards cardiac hypertrophy in these mice, suggesting its therapeutic efficacy in counteracting adverse remodeling." (PMID 35053329, 2022). "Furthermore, to validate the expression of hypertrophy-related gene expression in ARVs treated cardiomyocytes, we selected Hopx, Ackr3, and P2rx4 genes, based on their significance and the relatedness to their role in cardiac hypertrophy." (PMID 34943964, 2021).
depression (4 papers, 2017 to 2024). "This mouse should therefore be a useful tool to the research community for interrogations about ACKR3 and its critical roles in angiogenesis, inflammation, cancer and psychiatric diseases like depression and addiction." (PMID 34583741, 2021).
prostate tumor (4 papers, 2014 to 2020). "ACKR3 expression at the protein level was elevated in aggressive prostate tumors, where ACKR3 can increase the expression of pro-angiogenic factors such as CXCL8 and VEGF and support the transendothelial migration of cancer cells." (PMID 32456359, 2020).
Arthritis (3 papers, 2020 to 2022). Inflammation of a joint. "Meanwhile, ACKR3/CXCR7 has been demonstrated to play a role in angiogenesis in an animal model of arthritis." (PMID 33150252, 2020).
cervical cancer (3 papers, 2022). A primary or metastatic malignant neoplasm involving the cervix. "In HPV-associated cancers such as cervical cancer, GPCRs can be activated by the interaction of chemokines CXCR4 and ACKR3 with glycosaminoglycans of the extracellular matrix (ECM), acting as targets of oncogenic pathways at the cellular level of cancer cells and TME." (PMID 35879796, 2022).
epilepsy (3 papers, 2019 to 2021). A brain disorder characterized by episodes of abnormally increased neuronal discharge resulting in transient episodes of sensory or motor neurological dysfunction, or psychic dysfunction. "Notably, silencing ACKR3 in the hippocampal DG region has been shown to have an antiepileptic effect in a mouse model of epilepsy suggesting important neuronal regulatory functions for ACKR3." (PMID 34583741, 2021).
experimental autoimmune encephalomyelitis (3 papers, 2011 to 2020). An autoimmune demyelinating disease of the central nervous system that is produced experimentally in animals by the injection of homogenized brain or spinal cord in Freund's adjuvant. "Moreover, inflammation augments ACKR3 expression on the abluminal surface of the brain microvessel endothelium, contributing to damage in the context of experimental autoimmune encephalomyelitis (EAE), and blocking ACKR3 decreases the damage to primary brain endothelial cells in vitro." (PMID 30800123, 2019).
hyperlipidemia (3 papers, 2015 to 2022). "Moreover, systemic genetic ablation of ACKR3 was shown to cause hyperlipidemia in Apolipoprotein E deficient (Apoe−/−) mice, whereas its activation through CCX771 injections in mice decreased serum cholesterol and triglyceride levels." (PMID 33917642, 2021). "In order to fill this gap and to pinpoint cell-specific effects of ACKR3, we developed adipocyte and hepatocyte-specific ACKR3-deficient mice on an Apoe−/− background, which are prone to develop hyperlipidemia on WD, to determine whether ACKR3 can alter tissue lipid levels." (PMID 33917642, 2021). "The finding that ACKR3 knockout effectively reduces lipid uptake in the AT under hyperlipidemia reflects a beneficial physiological advantage for the AT as this process intervenes with excess lipid accumulation in the tissue, which could otherwise lead to a dysfunctional AT." (PMID 33917642, 2021).
lung squamous cell cancer (3 papers, 2018 to 2022). "Others showed that ACKR3 was upregulated in lung squamous cell carcinoma and downregulated by PPAR-γ." (PMID 35674847, 2022). "Interestingly, ACKR3 (formerly CXCR7) is an atypical receptor of CXCL11 and CXCL12, that is not expressed on peripheral blood leukocytes but upregulated by various tumor types, including breast, esophageal and lung squamous cell cancer." (PMID 30319622, 2018).
lymphedema (3 papers, 2021 to 2023). Excess fluid collection in tissues, causing swelling. "Specifically, ACKR3-deficiency was shown to result in lymphatic hyperplasia and lymphedema, in addition to cardiac hyperplasia and cardiac valve defects leading to embryonic lethality." (PMID 33857173, 2021). "Global loss of ACKR3 resulted in lymphatic vessel hyperplasia and hyperproliferation in E13.5 embryos and an embryonic lymphedema phenotype." (PMID 33857173, 2021). "Moreover, ACKR3-deficient embryos display lymphatic hyperplasia and lymphedema, a phenotype that has been attributed to ACKR3’s role as a scavenging receptor for AM in LECs." (PMID 37252916, 2023). "Consequently, loss of ACKR3 resulted in an overabundance of AM, leading to overshooting responses of LECs towards AM, what seemed to explain the lymphatic hyperproliferation and lymphedema phenotype observed in ACKR3-deficient mouse embryos." (PMID 33857173, 2021). "Thus, lymphatic-specific loss of ACKR3 did not result in any morphologic or functional differences that would be indicative of a lymphedema phenotype in adulthood." (PMID 33857173, 2021).
Myocardial fibrosis (3 papers, 2022 to 2025). "Decrease of myocardial function in Ackr3−/− was paralleled by a substantial enhanced myocardial fibrosis in Ackr3−/− compared to Ackr3fl/fl mice." (PMID 35383158, 2022).
viral infections (3 papers, 2011 to 2024). "The marked increases in Ccr2, Ccr5, Pld1, and Ackr3 produced by either AMPH or EIH observed in vivo provide further insight into the initial immune system alterations that result from methamphetamine and AMPH abuse and could modify risk for HIV and other viral infections." (PMID 30779732, 2019).
ductal carcinoma (2 papers, 2018 to 2021). "ACKR3 staining followed the same pattern as CXCR4—in ductal carcinoma ACKR3 was exclusively present in the cytoplasm and although it was also mostly cytoplasmic in lobular carcinoma, infiltrating cells also presented nuclei staining." (PMID 30441765, 2018).
invasive ductal carcinoma (2 papers, 2014 to 2018). "CXCR4 and ACKR3 expression was assessed in patient samples with invasive ductal carcinoma (left) and invasive lobular carcinoma (right) using immunohistochemistry." (PMID 30441765, 2018).
myocardial ischemia (2 papers, 2022 to 2024). A disorder of cardiac function caused by insufficient blood flow to the muscle tissue of the heart. "This indicates that similar to myocardial ischemia, loss of platelet-ACKR3 results in substantial cerebral inflammation." (PMID 35383158, 2022). "However, when mice were treated with roxadustat in the presence of myocardial ischemia, we observed a significant increase in mRNA levels for CXCL12, CXCR4, and ACKR3." (PMID 38994928, 2024).
pneumonia (2 papers, 2022 to 2024). An acute, acute and chronic, or chronic inflammation focally or diffusely affecting the lung parenchyma, caused by an infection in one or both of the lungs (by bacteria, viruses, fungi, or mycoplasma.). "Increased transcription of chemokine receptors CCR2 (CCL2/monocyte chemoattractant protein-1 (MCP-1) receptor) and CCR5 (CCL3/MIP-1A receptor) were observed, indicating that these inflammatory signals were activated, but receptors XCR1, CCR4, and ACKR3 were downregulated in the pneumonia group." (PMID 36119044, 2022).
preeclampsia (2 papers, 2021 to 2024). Preeclampsia is a hypertensive disorder of pregnancy that is characterized by new-onset hypertension with proteinuria presenting after 20 weeks of gestation, and depending on mild or severe forms may initially present with severe headache, visual disturbances, and hyperreflexia. "Notably, previous studies have shown that decreased ACKR3 expression in placentas and increased CXCL12 levels in blood were observed in pregnant women diagnosed with preeclampsia." (PMID 38300826, 2024).